COL11A1 (collagen type XI alpha 1 chain)
Diseases named in the same sentence as COL11A1 in open-access papers (continued):
Sharing a sentence is not in itself a finding about the gene and the disease.
non-small cell lung carcinoma (14 papers, 2013 to 2025). A group of at least three distinct histological types of lung cancer, including non-small cell squamous cell carcinoma, adenocarcinoma, and large cell carcinoma. "COL11A1 overexpression significantly correlated with pathological stage in non-small-cell lung cancer." (PMID 39845732, 2025). "Previous studies have showed that COL11A1 induces chemoresistance in epithelial ovarian cancer and non-small cell lung cancer." (PMID 38806505, 2024). "Several reports have also validated that COL11A1 is an oncogene in the progression of non-small cell lung cancer." (PMID 38649961, 2024). "Several reports also validate that COL11A1 is an oncogene in the progression of non-small cell lung cancer (NSCLC)." (PMID 35892083, 2022). "Overexpression of COL11A1 was also found in non-small cell lung cancer tissue samples where it correlates with pathological stage, presence of lymph node metastasis, and poor prognosis." (PMID 30227835, 2018). "Upregulation of COL11A1 has been described in several cancers, including colorectal, breast and non-small cell lung cancer." (PMID 28331057, 2017). "COL11A1 and ITGAX have both been previously related to tumor stage for other cancers (eg, melanoma, non-small cell lung cancer), but there are no reports for UNG and metastasis." (PMID 23717493, 2013).
osteoarthritis (11 papers, 2013 to 2025). A noninflammatory degenerative joint disease occurring chiefly in older persons, characterized by degeneration of the articular cartilage, hypertrophy of bone at the margins and changes in the synovial membrane. "Previous animal experiment also showed Col11a1‐OE mice demonstrated lower susceptibility to osteoarthritis and joint damage, indicating the therapeutic potential of COL11A1 in DDH treatment." (PMID 38314968, 2024). "Meanwhile, COL11A1 mutant loci have been implicated in osteoarthritis, lumbar disc degeneration and other degenerative musculoskeletal diseases." (PMID 38314968, 2024). "Meta‐analysis showed missense variation of COL11A1, SNP rs2126643 and rs3753841, were associated with osteoarthritis in Icelandic and UK population." (PMID 38314968, 2024). "For instance, the human ortholog of Acan, Col2a1, and Col11a1 are linked to spondyloepiphyseal dysplasia, osteoarthritis, disc degeneration, and susceptibility to lumbar disc herniation." (PMID 28011632, 2017). "The single nucleotide polymorphism (SNP) rs2615977 is associated with osteoarthritis (OA) and is located in intron 31 of COL11A1, a strong candidate gene for this degenerative musculoskeletal disease." (PMID 23497244, 2013). "An OSA patient who carries the COL11A1 risk allele may be more likely to suffer severe back pain or osteoarthritis, thus ending up on long-term opioids." (PMID 40649133, 2025). "Further analysis of these enriched pathways in injurious hydrostatic pressure highlighted differential expression of several genes known to be involved in osteoarthritis, such as Fgf2, Ep300, Ngf, Adam9, Igfbp3, Sox9, Comp, Col6a1, Col6a2 and Col11a1." (PMID 38144567, 2023). "Eight DXA area loci associate with osteoarthritis, including rs143384 in GDF5 and a missense variant in COL11A1 (rs3753841)." (PMID 31053729, 2019). "In addition, several genes known to play a key role in progression of osteoarthritis (e.g., Fgf2, Ep300, Ngf, Adam9, Igfbp3, Sox9, Comp, Col6a1, Col6a2 and Col11a1) were modulated in our injurious hydrostatic pressure hip cap datasets, thereby validating this approach." (PMID 38144567, 2023).
retinal detachment (11 papers, 2017 to 2025). An eye emergency condition which may lead to blindness if left untreated. "Most cases are dominantly inherited through COL2A1/COL11A1 variants encoding type-II/XI collagen, with patients having up to 78% retinal detachment (RD) risk." (PMID 39406934, 2025). "The most prevalent pathogenic genes for high myopia with retinal detachment were Stickler-related genes, including COL2A1 (10.0%, 4/40) and COL11A1 (5.0%, 2/40)." (PMID 40270540, 2025). "Pigment deposits in the anterior vitreous have also been suggested as a predictor of retinal detachment, an abnormality noted in an OES found to be heterozygous for the COL11A1 variant." (PMID 38153936, 2023). "Retinal detachment was present in 29 (29/42, 69%) probands, 20 (20/27, 74%) of whom had COL2A1 mutations, and 4 (4/8, 50%) had COL11A1 mutations." (PMID 32756486, 2020).
breast tumors (10 papers, 2006 to 2025). "Our findings reveal that COL11A1 mRNA and protein expressions are heightened in primary breast tumors relative to their normal counterparts." (PMID 39845732, 2025). "We compared the differentially expressed genes between the four types of organ metastases and primary breast tumors and identified genes such as COL11A1, MMP11, and THBS2 as more frequently differentially expressed in metastatic sites." (PMID 40500539, 2025). "COL3A1, COL5A1 and COL11A1 are fibrillar collagens, which act as “tracks” for metastatic invasion of breast tumors into secondary organs." (PMID 23383328, 2013). "Additionally, we noted a reduction in COL11A1 expression levels in lymph node metastases relative to their corresponding primary breast tumors, a phenomenon that remains unexplained currently." (PMID 39845732, 2025). "Notably, COL1A1 and COL11A1 transcripts demonstrated high discrimination between normal breast tissue and breast tumors." (PMID 39716322, 2024). "The expression of pro-COL11A1 presents, therefore, a significantly higher capacity to determine the microinfiltration (p < 0.0001) than calponin or p63, with a sensitivity of 94% and a specificity of 97% when used as a marker of infiltration in breast tumors." (PMID 37760937, 2023).
glaucoma (10 papers, 2016 to 2025). Increased pressure in the eyeball due to obstruction of the outflow of aqueous humor. "PLEKHA7 and COL11A1 were genotyped for single-nucleotide polymorphisms (SNPs) to investigate the possible association of these two genes with primary angle-closure glaucoma (PACG) and disease severity." (PMID 30809385, 2019). "A recent GWAS study found significant association of a single nucleotide polymorphism in COL11A1 with primary angle-closure glaucoma." (PMID 27484908, 2016). "Cross-referencing with human genome-wide association studies data revealed overlap with glaucoma-associated genes (LTBP2, LOXL1, COL11A1, VCAM1), alongside reduced expression of Angpt and Lmx1b, linked to ocular hypertension." (PMID 41443436, 2025). "In contrast, COL11A1 (FC = −1.96), which is associated with both POAG and primary angle closure glaucoma (PACG) was downregulated in WTβ3cells." (PMID 34440692, 2021). "It was also reported that the COL11A1 gene was upregulated in the lamina cribrosa of glaucoma patients, which further indicates the involvement of the expression and regulation of ECM genes in glaucoma pathogenesis." (PMID 30809385, 2019). "The nsSNP that gave rise to the next most negative mean iHS was found in the collagen 11 alpha 1 (COL11A1) gene, associated with primary open-angle glaucoma." (PMID 28774272, 2017).
ovarian tumors (10 papers, 2015 to 2023). "We demonstrated the importance of miR-335 in decreasing the occurrence of COL11A1-mediated ovarian tumor progression, chemoresistance, and the likelihood of poor survival." (PMID 37386587, 2023). "The COL11A1 and miR-509-3p mRNA expression levels of 161 ovarian tumors were determined by real-time reverse transcription-polymerase chain reaction." (PMID 36865240, 2023). "Our findings have therapeutic implications for clinicians who wish to treat ovarian tumors that maintain high levels of COL11A1 and HSP27." (PMID 34638339, 2021). "This study highlighted the importance of miR-335 in downregulating COL11A1-mediated ovarian tumor progression, chemoresistance, and poor survival and suggested its potential application as a therapeutic target." (PMID 34944877, 2021). "Nevertheless, its precise mechanism of action and the regulation of COL11A1 remain unexplored in ovarian tumors." (PMID 34944877, 2021). "It is also possible that there is synergism between Notch3-mediated and Notch3-independent changes in adhesion, in particular upregulation of COL11A1, which is unaltered by Notch3 signaling but associated with poor survival in human HGSC and ovarian tumor progression in mouse models." (PMID 32525899, 2020). "Varying mRNA and protein expression levels of COL11A1 at different stages and sites of the tumor suggests COL11A1 as a potential biomarker, with the highest COL11A1 levels detected in late stage disease (recurrent metastases) and lowest levels in earlier stage disease (primary ovarian tumors)." (PMID 26579497, 2015). "According to the HPA, high expression of CAV2, COL11A1, DNAJB4, THY1 and VCAN decreased the 5-year survival for breast, CNS, colon, kidney, lung and ovarian tumors." (PMID 37986165, 2023). "In recurrent ovarian tumors, CPT1A expression was positively correlated with COL11A1 expression." (PMID 32312965, 2020).
colon adenocarcinoma (9 papers, 2014 to 2025). "The expression of collagen 11A1 (COL11A1) by CAFs in several carcinoma types, including breast, kidney, ovarian and colon adenocarcinoma, has been associated with an adverse outcome." (PMID 32878206, 2020). "The TIMER analysis reveals that the comparison of the COL11A1 gene across various cancer types including colon cancer and displays that it is significantly upregulated for colon adenocarcinoma." (PMID 33597969, 2021). "The survival assay of the correlated genes shows similar significance to that of the COL11A1 gene in the colon adenocarcinoma dataset." (PMID 33597969, 2021). "We have presently shown, extending our previous observations, that procollagen 11A1, as a protein expression product of the COL11A1 gene, is immunodetected in stromal cells of human colon adenocarcinoma." (PMID 25417197, 2014). "In a recent study, the high expression of COL11A1 was positively correlated with CD4+T and CD8+T cells, tumor-associated macrophages (TAM), neutrophils and dendritic cells in colon adenocarcinoma, while the function of these immune cells in colon adenocarcinoma TME has not been identified." (PMID 36389832, 2022). "In several cancer types, COL11A1 correlates with multiple immune cells infiltration, such as macrophage, neutrophil, Th2 and dendritic cells in pancreatic adenocarcinoma, T cells, macrophages, neutrophils and dendritic cells in colon adenocarcinoma." (PMID 35892083, 2022). "Only KLK6, COL11A1, and WNT2 has been found to be suitable prognostic predictors for colon adenocarcinoma." (PMID 35883559, 2022). "The human COL11A1 gene has been shown to be up-regulated in stromal cells of colorectal tumours, but, so far, the immunodetection of procollagen 11A1, the primary protein product of COL11A1, has not been studied in detail in human colon adenocarcinomas." (PMID 25417197, 2014).
chondrodysplasia (8 papers, 2014 to 2023). "Variations in genes encoding cartilage collagens II and XI, COL2A1 and COL11A1, have been associated with chondrodysplasias, which are often associated with Robin sequence, micrognathia, or cleft palate." (PMID 37745857, 2023). "Mutations that reduce or modify COL11A1 gene expression cause milder forms of chondrodysplasia in Stickler’s and Marshall’s syndrome." (PMID 36278545, 2022). "In the cho/cho mouse, a model for chondrodysplasia, the result of a mutation in Col11a1 is dwarfism, with both chondrogenesis and endochondral ossification affected." (PMID 32872105, 2020). "In mice, a Col11a1 mutation causing a hereditary recessive chondrodysplasia (cho/cho) has provided key insight into the role of Col11a1 in the formation of cartilaginous structures." (PMID 32872105, 2020). "This is further supported by studies in mouse showing that mice homozygous for a spontaneous frameshift pathogenic variant in Col11a1 have severe chondrodysplasia and die at birth." (PMID 30245514, 2019). "The neonatal-lethal, homozygous cho/cho mouse features a severe chondrodysplasia caused by a point deletion in the COL11A1 gene, leading to a reading frame shift and the premature termination of the translation of the COL11A1 protein." (PMID 28335520, 2017). "In addition, clinical samples and animal models have indicated a clear link between chondrodysplasia, chain misassembly, and COL11A1 gene defects." (PMID 36278545, 2022). "LOXL3 knockout mice, which was different from COL2A1 and COL11A1 gene mutant mice, presented with spinal deformity but no dwarfism characteristic of chondrodysplasia." (PMID 26307084, 2015).
colon cancer (8 papers, 2008 to 2023). "This work presents the usefulness of COL11A1 in the differential diagnosis of infiltration in colon cancer." (PMID 37760937, 2023). "Considering COL11A1 molecular mechanisms in colon cancer, we designed the experiments to determine the effects of COL11A1s on cancer-related cellular behaviors, which is a novelty of this study compared with the previous reports." (PMID 35669376, 2022). "Numerous studies have shown the proliferative role of collagen signals, COL1A1 and COL11A1, in gastric, breast and colon cancers." (PMID 34824625, 2021). "From our data, it was evident that the promoter methylation of the COL11A1 gene is overexpressed in the colon cancer tissue than that of the normal tissue, and is negatively regulated for all other clinicopathological parameters." (PMID 33597969, 2021). "The diverse expression levels of core exon probe sets in COL11A1 between colon cancer and MG-thymoma tumors may unveil many unknown smaller transcripts, relevant to different types of cancer." (PMID 18545673, 2008). "Moreover, miR-29 is involved in colon cancer progression by targeting COL11A1." (PMID 34944877, 2021). "Moreover, miR-29 is likely involved in colon cancer progression by downregulating COL11A1." (PMID 34944877, 2021). "The results also supported that SPP1, COL11A1, ADAM12, and INHBA expressions were significantly higher in colon cancer tissues compared to that of the normal tissues in accordance with our previous study." (PMID 30746900, 2019). "Second, we did not process in-depth research to identify COL11A1 downstream regulations in colon cancer." (PMID 35669376, 2022). "We found that SPP1, VIP, COL11A1, CA2, ADAM12, INHBA could provide great significant prognostic value for colon cancer." (PMID 30746900, 2019).
keloid (7 papers, 2020 to 2026). An irregularly shaped, elevated mark on the skin caused by deposits of excessive amounts of collagen during wound healing. "According to the findings of RNA sequencing, COL5A2, COL10A1, and COL11A1 have been reported to be upregulated in keloid, as in our study." (PMID 37082197, 2023). "We intersected DEGs in keloid samples and shBRCA1 normal DF samples and obtained 13 overlaps, including some well-known keloid or other fibrotic disease-related genes, such as COL11A1 and NEDD4L." (PMID 36015648, 2022). "We identified skeletal system development, ossification, and osteoblast differentiation-associated genes, such as COL11A1, COMP, and POSTN, which were significantly increased in keloid mesenchymal fibroblasts." (PMID 34140509, 2021). "COL11A1 has been found to be overexpressed in human keloid fibroblasts related to normal skin fibroblasts." (PMID 33932142, 2021). "Subsequent network topology analysis through CytoHubba identified six hub genes (IL6, POSTN, VCAN, COL11A1, HAPLN1, TNC) via three methods of calculation respectively (Closeness, Degree and EPC), representing key regulatory nodes in the keloid." (PMID 41544047, 2026). "Among them, the number of mesenchymal fibroblasts (a type of myofibroblasts) characterized by collagen type XI alpha 1 chain (COL11A1) and periostin (POSTN) expression, was increased in keloid compared with normal scars." (PMID 38622256, 2024). "In our present study, we screened bone/cartilage-related genes (COMP, ASPN, COL5A2, COL10A1, and COL11A1), transcription factor (FOXC1), and miRNA (miR-335-5p) in major fibrotic skin diseases including keloid and SSc." (PMID 37082197, 2023). "One of the characteristics of the mesenchymal fibroblasts in keloid is the high expression of secretory proteins such as POSTN, COMP, COL11A1, ASPN, and COL5A2." (PMID 34140509, 2021). "The top 50 DEGs in lesional versus normal skin comparison included products related to fibrosis and cartilage/bone-differentiation (ADAM12, ASPN, COL10A1, COL11A1, FBN2), previously reported to be dysregulated in keloids." (PMID 33329590, 2020). "However, expression of COL11A1 and POSTN is also observed during the normal wound healing process and is not specific to keloid formation." (PMID 38622256, 2024).
lumbar disc herniation (7 papers, 2013 to 2024). "A single-nucleotide polymorphism in COL11A1 has been found to have a significant relationship with lumbar disc herniation; in addition, decreased expression of COL11A1 has been associated with lumbar disc herniation and a greater severity of degeneration." (PMID 33494410, 2021). "Notably, common COL11A1 variants also have been associated with adult lumbar disc herniation and lumbar disc degeneration, as well as DXA-measured bone size, spinal stenosis, and spondylolisthesis." (PMID 38277211, 2024). "Furthermore, the common non-synonymous COL11A1 SNP rs1676486 is associated with another degenerative musculoskeletal disease, lumbar disc herniation (LDH)." (PMID 23497244, 2013). "The COL11A1 rs3753841 and/or COL11A2 rs1799907 variants have however been associated with lumbar disc herniation, limbus vertebra in gymnasts, lumbar spine stenosis, ossification of the posterior longitudinal ligament of the spine and rheumatoid arthritis." (PMID 36553626, 2022). "Several polymorphisms (COL11A1 rs3753841 and rs1676486, COL11A2 rs1799907) have been associated with lumbar disc herniation and rheumatoid arthritis." (PMID 28523640, 2017).